C2orf15 (chromosome 2 open reading frame 15)
Synonyms: MGC29762
Tractability: No criterion of Open Targets' tractability assessment is met for any kind of drug.
Gene: Protein-coding gene on chromosome 2 (99,141,235 to 99,151,683, forward strand). Ensembl gene ENSG00000273045.
Gene Ontology:
Molecular function: protein binding; RNA binding
Genetic constraint (gnomAD): Loss-of-function variants: 3 observed, 6.39 expected, observed/expected ratio (o/e) 0.47, 90% interval 0.21 to 1.21. That is too few expected variants to judge how well the gene tolerates losing a copy. Missense variants: 90 observed, 108.73 expected, observed/expected ratio (o/e) 0.83, 90% interval 0.7 to 0.99. Synonymous variants: 37 observed, 39.01 expected, observed/expected ratio (o/e) 0.95, 90% interval 0.73 to 1.25.
Homologues: Orthologues: chimpanzee C2AH2orf15 (99% identical), macaque C13H2orf15 (93% identical), pig C2orf15 (81% identical).
Diseases named in the same sentence as C2orf15 in open-access papers:
C2orf15 is named in the same sentence as 2 diseases in open-access papers, as found by Europe PMC text mining. Sharing a sentence is not in itself a finding about the gene and the disease. The quoted sentences say what the papers report.
breast carcinoma (2 papers, 2024). "Elevated expressions of FARS2 and TRUB2 have been noted in breast cancer tissues, and C2orf15 expression significantly correlates with breast cancer prognosis, although their link to ER status needs further investigation." (PMID 39720180, 2024). "We constructed a risk model based on the expression levels of these RBPs and found that ADAT2, C2orf15, SRP72, PAICS, RBMS3, APOBEC3G, NOA1, and ACO1 could be used for risk assessment in terms of breast cancer prognosis." (PMID 38783078, 2024). "By further analysing above EMT-related RBPs and AS in breast cancer tissues in TCGA, it was found that the expression levels of ADAT2, C2orf15, SRP72, PAICS, RBMS3, APOBEC3G, NOA1, ACO1 and the AS of TNC and COL6A3 were significantly correlated with the prognosis of breast cancer patients." (PMID 38783078, 2024).
Obesity (1 paper, 2013). Accumulation of substantial excess body fat. "The rest of the candidates, C2orf15, DENND1B, MRPL30, POC1B, RP4-655J12.3, TMBIM4, BMP2 K, CSRNP2, NCKAP5L, TOMM5, and BAP1, may be novel genes related to T2DM or obesity." (PMID 24455749, 2013).